TIGIT (T cell immunoreceptor with Ig and ITIM domains)
Diseases named in the same sentence as TIGIT in open-access papers (continued):
Sharing a sentence is not in itself a finding about the gene and the disease.
leukemia (continued). "Staining for exhaustion markers LAG3 and TIGIT demonstrated an increase in expression on CD3+ T-cells in vehicle treated mice with leukemia between days 7 and 11, which is diminished by treatment with IL-12, generally consistent with the gene expression analyses." (PMID 35831470, 2022). "In addition, we detected increased expression of PD-L1 on the NFKBIE-ko leukemia cells as well as increased expression of PD-1, TIGIT and LAG3 on CD4+ and CD8+ T-cells from the spleens of mice with NFKBIE-ko tumors, consistent with the exhausted phenotype predicted by the RNAseq analysis." (PMID 38486128, 2024). "AML leukemia cells are characterized by high expression of CD155, which serves as the ligand for TIGIT." (PMID 40463500, 2025). "An extensive head-to-head comparison of CAR T cells with double knockdown of PD-1 and either LAG3, TIM3, or TIGIT in mice bearing NALM6 leukemia showed superior therapeutic efficacy of CAR T cells with simultaneous knockdown of PD-1 and TIGIT." (PMID 40558528, 2025). "The subsets showing a reduction in DNAM-1 expression and an increase in TIGIT expressing cells are expanded in AML patients, supporting a shift in the balance to inhibition of lymphocyte function, limiting its ability to fight leukemia blasts." (PMID 32764229, 2020). "Analysis of DNAM-1, TIGIT, TACTILE and PVRIG on human NK cells from solid cancer or leukemia patients will clarify the role of these receptors in cancer surveillance." (PMID 31234588, 2019). "Somewhat unexpectedly, we observed that despite this upregulation of inhibitory CRs, the blockade of TIGIT did not result in a significantly higher cytotoxicity of CIML-NK cells toward leukemia." (PMID 38967649, 2024). "TIGIT-high CD8+ T cells presented as functionally impaired and exhausted, whereas TIGIT blockade rescued functionality and anti-tumor response, highlighting TIGIT blockade as a potential therapeutic approach for leukemia." (PMID 36874131, 2023). "Therefore, the correlation of CD39, CTLA-4, TIGIT, TIM-3, and TNFR2 with Ki-67 suggested that their overexpression in Treg and/or exhausted CD8+ T cells of patients with ALL favors leukemia development and treatment resistance." (PMID 36901957, 2023). "Moreover, we suggest also that not only the cells that overexpress CTLA-4 and TIM-3, but even those that overexpress CD39, TIGIT, and TNFR2, favor B-ALL leukemia growth." (PMID 36901957, 2023). "Our finding that the expression of TIGIT and LAG3 is increased in marrow-infiltrating T cells supports specific evaluation of these targets, already under active investigation in adult cancers, in pediatric leukemia." (PMID 32692727, 2020). "Targeting TIGIT likely augments DNAM-1 dependent cytotoxicity and improves anti-leukemic activity, supporting the integration of exercise-enhanced DLI and γδ T-cell therapies with immune checkpoint blockade as a safe strategy to improve relapse control in leukemia." (PMID 41827731, 2026). "In our previous research, we found that the TIGIT expression of CD8+ T cells in the bone marrow and peripheral blood of AML patients was higher than that in HIs, suggesting that TIGIT may play an important role in T cell dysfunction in leukemia patients." (PMID 39391310, 2024). "Zhang’s research revealed that a single TIGIT inhibitor upregulated only IFN-γ and TNF-α, but the combination of anti-TIGIT and anti-PD-1 inhibitors significantly upregulated IL-2, IFN-γ, and TNF-α in CD4+ or CD8+ T cells, which could enhance anti-leukemia immune response." (PMID 37291608, 2023). "However, combined inhibition of TIGIT, PD-1, and Tim-3 significantly up-regulated IL-2, IFNγ, and TNFα in both CD4+ and CD8+ T cells, which may enhance anti-leukemia immune responses." (PMID 36605439, 2022). "Thus, the elevated TIGIT expression on the BM CD8+ T cells of DN, CR, and R/R patients may be mainly impacted by the leukemia microenvironment itself, while the BM microenvironment of elderly patients may further exacerbate the high expression of TIGIT." (PMID 34490086, 2021).
leukemia (continued). "In addition, we found that both DN and R/R patients accumulate a higher frequency of PD-1+ and TIGIT+ CD8+ T cells in BM than in corresponding PB, indicating that a more immunosuppressive microenvironment in leukemia BM may promote disease progression." (PMID 34490086, 2021). "In NK cells from patients with solid cancer and leukemia, it has been observed a decreased expression of DNAM-1 that may shift the balance in favor to the inhibitory receptors TIGIT or PVRIG, further contributing to the diminished NK cell-mediated cytotoxic capacity observed in these patients." (PMID 31234588, 2019).
Autoimmunity (24 papers, 2015 to 2026). The occurrence of an immune reaction against the organism's own cells or tissues. "TIGIT+ Tregs are a highly suppressive subset of T cells, often associated with immune tolerance, tissue protection, and restraint of autoimmunity." (PMID 41597269, 2026). "The role of T cell immunoglobulin and ITIM domain (TIGIT) in autoimmunity is increasingly recognized as a significant area of research, highlighting its potential as a therapeutic target." (PMID 41597269, 2026). "Simultaneously, the reduction in the percentage of exhausted TIGIT+ Tconvs suggests the inability of the system to maintain immune homeostasis, tipping the balance toward autoimmunity." (PMID 41597269, 2026). "In mouse models for multiple sclerosis (MS), TIM-1 or TIGIT expression on B cells is required for maintaining self-tolerance and regulating autoimmunity to the central nervous system." (PMID 38745667, 2024). "The role of TIGIT in maintaining immune tolerance by dampening effects of peripheral T cells has been studied widely in mouse models of autoimmunity." (PMID 35410311, 2022). "The roles of TIGIT in immune modulation holds promise for the development of efficient therapeutic strategies to treat autoimmunity." (PMID 35720417, 2022). "The TIGIT inhibitory pathway is known to play an important role in limiting autoimmunity as well as negatively regulating anti-tumor responses." (PMID 32152316, 2020). "Activation of co-inhibitory receptors, including CTLA-4, PD-1, LAG-3, TIM-3, and TIGIT, induce immune tolerance, therefore their stimulation would be beneficial in autoimmune disorders." (PMID 30564191, 2018). "In addition, modulating the DNAM-1/TIGIT axis is highly investigated as a therapeutic target in oncoimmunity, and can also be of interest to target autoimmunity to boost immunoregulation and reduce target-cell killing." (PMID 36979144, 2023). "The link between TIGIT+ T/NK cells and autoimmunity has been documented in the literature." (PMID 35720417, 2022). "In this review, we provide an overview of characteristics of TIGIT and its role in autoimmunity." (PMID 35720417, 2022). "The biological function of TIGIT was initially investigated in models of autoimmunity." (PMID 31974523, 2020). "Mice lacking T cell Immunoreceptor with Ig and ITIM domains (TIGIT) do not develop spontaneous autoimmunity but have increased susceptibility to experimental autoimmune encephalitis (EAE)." (PMID 30349540, 2018). "Co-inhibitory receptors, including cytotoxic T-lymphocyte associated protein 4 (CTLA-4), programmed cell death protein 1 (PD-1), lymphocyte-activation protein 3 (Lag-3), and TIGIT play an essential role in the prevention of autoimmune disorders by promoting tolerized responses." (PMID 30564191, 2018). "Moreover, loss of the inhibitory molecule TIGIT which competing for the same ligand with CD226, resulted in hyperproliferative T cell responses and increased susceptibility to autoimmunity." (PMID 26942885, 2016). "While TIGIT deficiency alone does not induce overt autoimmunity, TIGIT pathway blockade exacerbates several immune diseases." (PMID 26347741, 2015). "Additionally, a mouse model revealed that TIGIT can directly suppress T cell responses independent of antigen-presenting cells, and that loss of TIGIT in mice leads to increased susceptibility to autoimmunity." (PMID 36741366, 2022). "TIGIT-deficient mice do not develop spontaneous autoimmunity; however, they exacerbate experimental autoimmune encephalitis when immunized with myelin oligodendrocyte glycoprotein, indicating a suppressive role of TIGIT." (PMID 33670993, 2021). "Mice deficient for TIGIT did not display spontaneous autoimmunity." (PMID 31974523, 2020). "A recent study revealed that TIM1+ B cells express co-inhibitory molecules such as TIGIT, and that the TIM1-AhR-TIGIT axis is crucial for maintaining immune tolerance and preventing autoimmunity." (PMID 41511071, 2026).
Autoimmunity (continued). "As an immunomodulatory molecule, CD155 can combine with the costimulatory molecule CD226 and coinhibitory molecules TIGIT and CD96, therefore it plays a dual function in autoimmunity." (PMID 35720417, 2022). "Agonists targeting TIGIT and BTLA were both shown to inhibit ligand binding and to be capable of treating disease in models of autoimmunity." (PMID 30349540, 2018). "For instance, the absence of TIGIT on T cells does not directly induce autoimmunization; however, the blockade of signaling pathways triggered by TIGIT interactions with its receptors exacerbates several autoimmune conditions." (PMID 40574024, 2025). "Considering the involvement of TIGIT and NRP1 in T cell exhaustion and chronic inflammation, CUR’s modulation of this axis offers new perspectives for therapeutic intervention in other chronic autoimmune or inflammatory diseases characterized by T cell dysfunction." (PMID 41465029, 2025). "However, unlike CTLA-4 and PD-1, TIGIT knockout in mice does not result in a severe spontaneous autoimmune phenotype, suggesting that TIGIT moderates the immune response without triggering severe autoimmunity." (PMID 40356928, 2025). "Theoretically, TIGIT-blockade may be an interesting alternative for CTLA-4 blockade, because TIGIT knockout mice do not develop autoimmunity, while CTLA-4 knockout mice die within 2-3 weeks due to severe autoimmunity." (PMID 34367161, 2021).
liver cancer (23 papers, 2021 to 2025). An epithelial or non-epithelial malignant neoplasm that arises from the liver. "According to mRNA profiling of CD8+ T cells in a murine model of autochthonous liver cancer, TIGIT is a hallmark of T cell exhaustion in liver cancer at various stages of their differentiation." (PMID 35656508, 2022). "TIGIT expression promotes liver cancer progression through tumor-associated immune suppression." (PMID 38374893, 2024). "The TIGIT-NECTIN2 immune checkpoint axis is another key interaction in liver cancer, promoting the creation of an immunosuppressive microenvironment that supports cancer growth." (PMID 41031085, 2025). "For example, dysfunctional NK cells that express TIGIT in combination with lower levels of CD226 have been observed in liver cancer, correlate with disease prognosis and are increased in the periphery of hepatitis B-related HCC patients." (PMID 41451217, 2025). "Wang designed a novel polymerized nanoparticle that targets lncRNA INK4 as well as T cell immune receptors with Ig and ITIM domains (TIGIT)/poliovirus receptors (PVR) to inhibit liver cancer." (PMID 36968595, 2023). "Our study found that liver cancer patients in the high-risk group had high expression of some immune checkpoints (PD-1, PD-L1, CTLA4, B7-H3, VSIA, LAG3 and TIGIT)." (PMID 36081999, 2022). "A recent study in rodents concluded that TIGIT is the most reliable marker to detect and reverse exhausted Tex in liver cancer and also other studies show the importance of TIGIT as a target for immunotherapy in HCC patients." (PMID 34209393, 2021). "The results showed that the expression of TIGIT in tumor tissues was significantly higher than that in adjacent and normal tissues, and the expression of TIGIT in poorly differentiated liver cancer tissues was significantly higher than that in moderately and well-differentiated tissues." (PMID 37124530, 2023). "TIGIT is elevated on lymphocytes infiltrating liver cancer tissue and may participate in the tumor progression." (PMID 35433470, 2022). "The whole-cell vaccine for liver cancer targeting STAT3 reversed the depletion of T cells and NK cells in the liver cancer microenvironment, which may be attributed to the low expression of PD-1 and TIGIT." (PMID 35433470, 2022). "We infer that the combination of drugs that improve liver function and antiviral drugs may improve the excessive inflammation caused by the promotion of immunotherapy when immunotherapy targeting CD155/TIGIT is applied to HBV-related liver cancer." (PMID 35433470, 2022). "The role of TIGIT in liver cancer is still under investigation." (PMID 33995362, 2021). "Therefore, CD155/TIGIT is expected to become a novel target for liver cancer immunotherapy." (PMID 35433470, 2022). "However, TIGIT blockade or deletion reversed the tolerance of CD8+T cells to viral antigen, which caused chronic hepatitis in mice and eventually led to the development of liver cancer." (PMID 35433470, 2022). "The TIGIT-NECTIN2 axis can regulate the immunosuppressive environment and intercellular interaction in liver cancer, providing mechanism information for the effective treatment of this cancer." (PMID 38443340, 2024). "It has been reported that PVRL1 stabilized CD155 expression on the surface of liver cancer cells by reducing the endocytosis of CD155, and then interacted with TIGIT on the surface of CD8+ T cells." (PMID 35433470, 2022). "A recent study has shown that high expression of the TIGIT and TIM3 proteins in the NK cells of patients with liver cancer correlates with NK cell exhaustion and disease progression." (PMID 35856557, 2022). "The mRNA expression levels of immune checkpoint-related genes were significantly higher in the high-risk group than in the low-risk group, especially for immune checkpoint-related genes commonly used in liver cancer immunotherapy, including (PD-L1, PDCD1LG2, PDCD1, TIGIT, TIM-3, CTLA4)." (PMID 36814910, 2023).
liver cancer (continued). "designed a nanoparticle that blocked the binding of TIGIT and CD155 and targeted LncRNA ANRIL, which exhibited a significant anti-tumor effect and increased the proportion of NK cells and T cells in an in vivo model of liver cancer." (PMID 35433470, 2022).
viral infections (23 papers, 2016 to 2025). "Joller and colleagues show that the co-inhibitory receptor TIGIT induces the expression of the tissue growth factor amphiregulin (Areg) in regulatory T cells and contributes to tissue repair in response to viral infection." (PMID 41094201, 2025). "TIGIT seem to promote T cell dysfunction by altering their phenotype and cytokine profile during chronic viral infection." (PMID 40117286, 2025). "Consistent with an increase of T cell exhaustion in chronic as compared to acute viral infections, we found increased frequencies of TIGIT+KLRG1+ TEX in CMV- and EBV-specific T cells identified by pentamer reagents as compared to influenza-specific T cells." (PMID 38650930, 2024). "In severe viral diseases, the sustained expression of TIGIT in response to persistent antigen can result in T-cell exhaustion." (PMID 35432324, 2022). "TIGIT expression prevents immune pathologies of viral infections in mice and reduces lung damage in influenza infection." (PMID 36433939, 2022). "Previous studies have shown that TIGIT is involved in the immune response to tumor and viral infections." (PMID 35413989, 2022). "Joller and colleagues demonstrated that TIGIT engagement can limit T cell–driven inflammation and protect against immune pathology via induction of immune-modulatory cytokine IL-10 in acute viral infection model." (PMID 33682797, 2021). "In summary, these data reveal an important role of the TIGIT pathway in limiting immune-mediated tissue damage during acute virus infection in an IL-10-dependent manner." (PMID 32152316, 2020). "As TIGIT ligation is functionally linked to IL-10 expression that is known to both promote virus persistence in vivo, but also limit adverse immunopathological damage, the TIGIT pathway might represent an important regulatory gatekeeper for the control of viral infections." (PMID 32152316, 2020). "In this study, we investigated the significance of the TIGIT pathway in modulating T cell function during viral infections." (PMID 32152316, 2020). "The presence of TIGIT has been shown on exhausted T cells during viral infection and its expression positively correlates with disease progression." (PMID 30959825, 2019). "Recent studies have demonstrated that TIGIT, a co-inhibitory molecule, is expressed on tumor infiltrating T cells and T cells during viral infection, which suppresses the anti-tumor and anti-viral immune responses." (PMID 26735971, 2016). "As TIGIT can limit tissue damage during viral infection, we hypothesized that it may act as an additional signal promoting the repair functions of T cells." (PMID 41094201, 2025). "Data from LCMV infection mouse model also revealed a gradual upregulation of TIGIT expression during viral infection and sustained at a high level on LCMV-specific CD4+ and CD8+ T cells during chronic phase of infection in response to continuous TCR stimulation." (PMID 40526725, 2025). "Overall, TIGIT appears to diminish T cell effector function, either through the induction of IL-10 production or via other mechanisms, particularly in the context of persistent viral infections." (PMID 40872232, 2025). "Cluster 5 is related to immune tolerance to viral infections, and its subclusters 5–14 are related to TIGIT and CD155, which are considered to be the third molecules for immune checkpoints following PD-1/PDL-1 and CTLA4/CD80/86, whose inhibitors have already been used in pharmaceuticals." (PMID 34811710, 2022). "Similarly, we found that TIGIT stimulation during acute viral infection only temporarily impacts viral titers, as the virus was generally cleared by day 14 p.i. despite elevated virus loads in the spleen, but not the liver at an early time point (day 5 p.i.)." (PMID 32152316, 2020). "In a first line of investigation, we sought to identify whether TIGIT is expressed on exhausted T cells upon chronic viral infection with LCMV clone 13, the classical model to study T cell exhaustion and viral persistence." (PMID 32152316, 2020).